TSC2 (TSC complex subunit 2)
Diseases named in the same sentence as TSC2 in open-access papers (continued):
Sharing a sentence is not in itself a finding about the gene and the disease.
infantile epilepsy (2 papers, 2016 to 2023). "The TSC2 c.3846_3855delinsG variant has been identified in several other individuals with infantile epilepsy who are without clinical features of TSC (Panzer, 2015, unpublished data)." (PMID 26703369, 2016). "Only a candidate variant (c.2742+5G>A, rs397515076) was found in a heterozygous state in the TSC2 gene, and no candidate variant was detected in the TSC1 gene or other infantile epilepsy-related genes." (PMID 37152430, 2023).
low grade glioma (2 papers, 2019 to 2021). A grade I or grade II glioma arising from the central nervous system. "Apart from PPGL, low-grade glioma (LGG) also exhibits a significant negative correlation between miR-21-3p and TSC2 (ρ=-0.18, P=1.3·10-4), as well as a positive one with pS6 levels (in Ser235/236: ρ=0.27, P=1.7·10-8; in Ser240/244: ρ=0.23, P=6.6·10-7)." (PMID 31410193, 2019).
lymph node metastasis (2 papers, 2008 to 2022). "Loss of ATRX or TSC2 has been significantly associated with lymph node metastasis, and combined loss of TSC2 and ATRX has been determined as an independent prognostic factor for shorter RFS in G2 pNENs." (PMID 36556070, 2022).
medulloblastoma (2 papers, 2023). A malignant, invasive embryonal neoplasm arising from the cerebellum. "To date, only medulloblastoma in Ptch1+/− mice and renal tumors in Tsc2+/− Eker rats have been properly demonstrated (i.e. with evidence of copy number losses) to have an interstitial deletion as a radiation signature in solid tumors." (PMID 37117033, 2023).
mesenchymal tumors (2 papers, 2020 to 2023). "Adding that only 50% of human mesenchymal tumors, and 31% of Tsc2+/− mouse renal tumors exhibit altered mTOR pathway activation, supports the existence of tumorigenic mTOR-independent mechanisms causing LAM pathogenesis." (PMID 32365712, 2020). "Cytogenetic studies in the Tsc2+/− mouse mesenchymal tumors will determine whether chromosomal rearrangements play a pathogenic role in these LAM mouse models." (PMID 32365712, 2020).
multiple endocrine neoplasia (2 papers, 2020 to 2023). Multiple endocrine neoplasia (MEN) is a group of rare inherited cancer syndromes characterized by the development of two or more endocrine gland tumors, sometimes with tumor development in other tissues or organs. "Furthermore, although the majority of NETs are sporadic tumors, a proportion of them (10–15%) are attributable to familial cancer syndrome, like Multiple Endocrine Neoplasia (MEN) 1 and 2, von-Hippler-Lindau Syndrome and Tuberous Sclerosis Complex 1 (TSC-1) and Tuberous Sclerosis Complex 2 (TSC-2)." (PMID 32397669, 2020).
Multiple renal cysts (2 papers, 2020 to 2026). The presence of many cysts in the kidney. "Atypical findings (e.g., calcification or necrosis) warrant early biopsy; non-diagnostic sequencing requires copy-number analysis (e.g., chromosomal microarray) to detect TSC2 deletions in TSC-featured patients and multiple renal cysts." (PMID 41727759, 2026).
oral cancer (2 papers, 2016 to 2020). "Till date no studies have found an association between TSC and oral cancer; however TSC-2 overexpression may exert antitumor effect due to its oncosuppressor genes." (PMID 26885413, 2016).
Pleural effusion (2 papers, 2022 to 2025). The presence of an excessive amount of fluid in the pleural cavity. "Pathogenic CNV in 16p13.3 (33.98 kb deletion) altered TSC2 and PKD1 genes that were postulated to contribute to driving ascites and pleural effusion." (PMID 34980134, 2022). "STLAM6 exhibited similar systemic involvement, including pleural effusions, chylothorax, and abdominal lymphadenopathy, with a 49% FGFR4 variant frequency, but no detectable TSC2 mutation." (PMID 40776927, 2025).
prostate tumor (2 papers, 2014 to 2020). "Further work has also indicated that inactivation of tuberous sclerosis 2 (TSC2) is required for PTEN-dependent prostate tumor growth." (PMID 33105713, 2020). "We next carried out western analysis of TSC2 protein expression in a panel of PCa tissues to determine if TSC2A protein is expressed within clinical prostate tumours." (PMID 24318044, 2014).
retinoblastoma (2 papers, 2011 to 2021). A malignant tumor that originates in the nuclear layer of the retina. "Of the non-RB1 gene alterations in our cohort, only MYCN on 2p24.3 and TSC2 on 16p13.3 correspond with common CNVs that characterize retinoblastoma." (PMID 33466343, 2021).
rosacea (2 papers, 2021). A chronic erythematous skin disorder that affects the face. "On the contrary, hyperactivation of mTORC1 signaling in TSC2+/− mice exacerbated rosacea development." (PMID 33734592, 2021). "Here, we showed that TSC2 rather than TSC1 was significantly decreased in the lesional skin of rosacea, suggesting that declined TSC2 might be responsible for the hyperactivation of mTORC1 in rosacea." (PMID 33734592, 2021).
thyroid cancer (2 papers, 2018 to 2019). "However, in the thyroid cancer extraordinary responder case study, the tumor gained resistance to rapalog treatment as it acquired a mutation in mTOR, which prevented the binding of the rapalog, as well as a nonsense mutation in TSC2." (PMID 30764584, 2019). "Furthermore, heightened treatment sensitivity was associated with TSC1 or TSC2 LOF mutations, as reported in bladder and thyroid cancer." (PMID 30764584, 2019).
viral infection (2 papers, 2022). "Moreover, changes in the human phosphoproteome upon viral infection highlighted several RSK target proteins in addition to c-FOS and EIF4B, such as 40S ribosomal protein S6, Tuberin/TSC2, or GSK347." (PMID 35078976, 2022).
acute leukemia (1 paper, 2022). A clonal (malignant) hematopoietic disorder with an acute onset, affecting the bone marrow and the peripheral blood. "This is opposite to what has been shown for TSC2 expression in acute leukemia." (PMID 36400754, 2022).
Alpha-thalassemia (1 paper, 2015). Alpha-thalassemia is an inherited hemoglobinopathy characterized by impaired synthesis of alpha-globin chains leading to a variable clinical picture depending on the number of affected alleles. "Note that these TSC2 gene mutations have not been detected as frequently as multiple endocrine neoplasia type 1 (MEN1) and death domain-associated protein/alpha thalassemia/mental retardation syndrome X-linked (DAXX/ATRX) gene mutations." (PMID 25889454, 2015).
aneurysm (1 paper, 2022). Bulging or ballooning in an area of an artery secondary to arterial wall weakening. "To clarify the mechanism whereby aneurysm development was exaggerated in AngII-infused Tsc2MKOApoE–/– mice, we first identified the genes that are regulated by Tsc2 in macrophages following AngII infusion." (PMID 36400753, 2022). "Of interest, increased expression of multiple genes in Tsc2 deficient macrophages including Mmp9, Fosl1, Fos and TSP-1 were involved as the downstream targets of CREB and associated with aneurysms formation." (PMID 36400753, 2022). "As revealed by immunofluorescence staining, Tsc2 deletion in myeloid cells significantly decreased the expression of contractile SMC phenotype marker sm22α but increased the synthetic phenotype marker vimentin in aneurysm tissues." (PMID 36400753, 2022). "Thus, we aimed to evaluate the role of macrophage Tsc2 in vascular inflammation and aneurysm pathogenesis." (PMID 36400753, 2022).
angiolipoma (1 paper, 2008). A lipoma with prominent vascularity. "An alternative explanation is that the TSC2 447C>G (F143L) substitution does have an effect on TSC2 function, sufficient to allow the formation of angiolipoma." (PMID 18302728, 2008).
aortic aneurysm (1 paper, 2022). A ruptured aneurysm located in the wall of the proximal portion of the descending aorta proceeding from the arch of the aorta. "Tsc2 deletion induced pro-aneurysmal phenotype was consistent with the clinical studies that patient with Tsc2 mutation lead to aortic aneurysms formation." (PMID 36400753, 2022). "Gpr68 inhibition largely abrogated the progression of aortic aneurysms caused by Tsc2 deficiency in macrophages." (PMID 36400753, 2022). "The findings reveal that Tsc2 deficiency in macrophages contributes to aortic aneurysm formation, at least in part, by upregulating Gpr68 expression, which subsequently drives proinflammatory processes and matrix metallopeptidase activation." (PMID 36400753, 2022). "Therefore, small molecule agents could be designed to block macrophage Gpr68 signaling to prevent aortic aneurysm development especially in patient with Tsc2 mutation." (PMID 36400753, 2022). "Genetic studies have proved the involvement of Tuberous sclerosis complex subunit 2 (Tsc2) in aortic aneurysm." (PMID 36400753, 2022). "Here, we examined the potential function of macrophage Tsc2 in the development of aortic remodeling and aortic aneurysms." (PMID 36400753, 2022). "One major finding of this study is that Tsc2 deletion in macrophages exacerbated aortic aneurysms formation." (PMID 36400753, 2022). "Further conditional Tsc2 knockout mice in other vascular cell types, as well as aortic aneurysms models will be more informative." (PMID 36400753, 2022). "Subsequently, to investigate whether macrophage Tsc2 is crucial to maintain vasculature homeostasis, we crossed myeloid-specifc Tsc2MKO with hyperlipidemic ApoE–/– mice and established AngII-induced murine aortic aneurysm model." (PMID 36400753, 2022). "In summary, our data demonstrate that Tsc2 deletion triggers a proinflammatory phenotype in macrophages through the Gpr68/CREB pathway, thereby aggravating aortic remodeling and aortic aneurysm formation." (PMID 36400753, 2022).
arachnoid cyst (1 paper, 2023). Intracranial or spinal cavities containing a cerebrospinal-like fluid, the wall of which is composed of arachnoidal cells. "In addition, the continuous deletion of the TSC2 and PKD1 genes increases the risk of an arachnoid cyst developing." (PMID 37679848, 2023).
Arthritis (1 paper, 2022). Inflammation of a joint. "Mice with induced deletion of Tsc2 spontaneously developed arthritis and an MAS-like syndrome characterized by cytopenia, elevated ferritin levels, and hepatosplenomegaly." (PMID 36443301, 2022). "Supporting this hypothesis, the pathology of IL1rn deficiency and CpG-induced MAS was largely abrogated by rapamycin treatment while unrestricted activation of mTORC1 in Tsc2 KO mice was sufficient to elicit an SD-like syndrome, including both arthritis and fulminant MAS." (PMID 36443301, 2022).
autoimmune disease (1 paper, 2022). A disorder resulting from loss of function or tissue destruction of an organ or multiple organs, arising from humoral or cellular immune responses of the individual to their own tissue constituents. "From a translational perspective, the results open opportunities to modulate TSC2-mTORC1 regulation in a more selective manner, with potential applications to cell therapies for cancer and autoimmune disease." (PMID 35288456, 2022).
bladder tumors (1 paper, 2017). "As TSC1 or TSC2 mutations occur in cancers, we sought to determine if the TSC2 loss-of-function expression signature was present in human bladder tumors since this tumor type often sustains inactivating TSC1 or TSC2 mutations." (PMID 28695825, 2017). "Interrogation of the TCGA cohort revealed that TSC1 and TSC2 mutant bladder tumors overexpressed LGALS3 versus other bladder tumors." (PMID 28695825, 2017). "Signature scores were greater in tumors having non-silent TSC1 or TSC2 mutations versus other bladder tumors indicating that these cancers have an identifiable gene expression signature derived from inactivation of TSC1 or TSC2." (PMID 28695825, 2017).
Carney syndrome (1 paper, 2022).
clear cell carcinomas (1 paper, 2019). "FAM129A expression was detected in Tsc1 and Tsc2 knockout mice, in sporadic human RCC including clear cell carcinomas, granular cell carcinomas and spindle cell carcinomas." (PMID 31016032, 2019).
Co-infection (1 paper, 2013). "Co-infection also affected expression of gigas, which produces the Tsc2 protein in the Drosophila insulin signaling pathway." (PMID 24245482, 2013).
cognitive decline (1 paper, 2024). "Here, we found that a substantial decrease of IEG expression during memory challenge and molecularly, an increase of markers of neurodegeneration and a decrease of expression of components of the mTOR/Akt1 signaling cascade are associated with the cognitive decline in aging Tsc2+/− animals." (PMID 39192595, 2024). "Our data shows that a continuously increased mTOR activity in a Tsc2+/− animal model with time leads to a substantial downregulation of molecules of the mTOR pathway and to premature cognitive decline." (PMID 39192595, 2024). "Our data suggests that early inhibition of mTOR might similarly be able to prevent overburdening of the synaptic mTOR signaling cascade and thereby abrasion of local protein synthesis and cognitive decline could be delayed in Tsc2+/− animals." (PMID 39192595, 2024). "Thus, a macroscopic degenerative process in the hippocampus can be excluded as an underlying cause for the cognitive decline in aged Tsc2+/− mice." (PMID 39192595, 2024). "In order to further validate the influence of Akt/mTOR/IGF2 downregulation on the cognitive decline phenotype, we investigated if IGF2 injection can rescue memory consolidation in aged Tsc2+/− mice." (PMID 39192595, 2024). "Only at 8–10 months of age, subtle cognitive aberrations were observed, suggesting a premature cognitive decline in the Tsc2+/− animals rather than a congenital defect in intellectual capability." (PMID 39192595, 2024). "The premature cognitive decline that we have observed, however, has not been described in animals or patients before, probably because longitudinal analysis of cognitive function in Tsc2+/− animals has not been performed until old age so far." (PMID 39192595, 2024).
communication disorder (1 paper, 2022). A disorder characterized by an individual's inability to comprehend or share ideas or feelings because of an impairment in language, speech, or hearing. "Nonetheless, a stark difference was observed in the prevalence of communication disorders between the groups, with TSC2 patients once again demonstrating a poorer outcome." (PMID 35440050, 2022). "Brain involvement was seen with increased severity in TSC2 patients, characterised by a greater prevalence of cortical tubers and communication disorders." (PMID 35440050, 2022). "Furthermore, a significant difference was found between the presentation of communication disorders in TSC1 and TSC2 at a prevalence of 6% and 50%, respectively (Z = −3.17, df = 1, p = 0.0015)." (PMID 35440050, 2022).
COVID-19 (1 paper, 2024). A disease caused by infection with severe acute respiratory syndrome coronavirus 2. "We subsequently identified two groups of specific DEPs: PPP2R5E, SGK3, CDC37, TSC2, and 20 other DEPs that were upregulated- or downregulated solely in the COVID-19 group, with no observed differences in the PQ group." (PMID 39301288, 2024).
craniopharyngioma (1 paper, 2019). A benign, partly cystic, epithelial tumor of the sellar region, presumably derived from Rathke pouch epithelium. "Both the PIK3CA and the TSC2 mutations were observed in two patients in our study, suggesting that the roles of PIK3CA and TSC2 merit further investigation as to their contributions to the etiology of craniopharyngioma." (PMID 31712784, 2019).
cutaneous sarcoma (1 paper, 2016). "CRL-2620 was originally obtained from a cutaneous sarcoma taken from a TSC2 +/- mouse." (PMID 26765535, 2016).
dilated cardiomyopathy (1 paper, 2016). Cardiomyopathy which is characterized by dilation and contractile dysfunction of the left and right ventricles. "Absence of fibrosis and cardiomyocyte death indicates that cardiac remodeling observed in TSC2-/- mice is not typical for general dilated cardiomyopathy." (PMID 27023784, 2016).
emphysema (1 paper, 2023). "Depletion of Tsc1 or Tsc2 in adult lung epithelium, smooth muscle, or vascular endothelium demonstrated that the activation of mTORC1 drove cell senescence, loss of lung alveolar structure, and the appearance of emphysema with pulmonary hypertension and significant vascular remodeling in male mice." (PMID 37874650, 2023).
endometrioid ovarian carcinoma (1 paper, 2025). "Additionally, we identified deletions in genes TSC2 and STK11 that have not been previously reported in endometrioid ovarian carcinoma." (PMID 40981433, 2025).
Epileptic encephalopathy (1 paper, 2024). A condition in which epileptiform abnormalities are believed to contribute to the progressive disturbance in cerebral function. "Gene set analysis revealed an upregulation of K-RAS signaling, glutamatergic synapse, and epileptic encephalopathy when comparing TSC2 mutant (TSP8-15) versus control (CC3) neural cells for RNA expression differences." (PMID 38783199, 2024).
fallopian tube carcinoma (1 paper, 2024). A carcinoma that arises from epithelial cells of the fallopian tube. "A report at the 2016 ASCO meeting showed a cohort of 379 patients with ovarian or fallopian tube carcinoma have been evaluated for 10 genes AKT1, AKT2, AKT3, mTOR, PIK3CA, PIK3C2B, PIK3R1, PTEN, TSC1, TSC2 in the PI3K/AKT/mTOR pathway." (PMID 38167649, 2024).
fibroma (1 paper, 2024). A non-metastasizing neoplasm arising from the fibrous tissue. "The chance of a TSC2 mutation was 10-fold higher in the presence of ungual fibromas, although these data should be viewed with caution because of the wide confidence interval associated with the small number of cases with a TSC1 mutation." (PMID 38658236, 2024). "A significant association between TSC2 gene pathogenic alterations and ungual fibromas is described." (PMID 38658236, 2024). "The authors describe in the TSC cohort a significant association between ungual fibromas and TSC2 alterations." (PMID 38658236, 2024). "The TSC cohort from a reference clinical center in Southern Brazil discloses the association between ungual fibromas and TSC2 genetic alteration." (PMID 38658236, 2024). "The frequency of a TSC2 pathogenic variant was 10-fold greater in the presence of ungual fibromas." (PMID 38658236, 2024).
focal cortical dysplasia type II (1 paper, 2023). "As mutations in TSC1 and TSC2, which cause partial-onset seizures associated with TSC, were found in focal cortical dysplasia type II (FCD II) patients, a clinical trial has been performed to explore the efficacy and safety of everolimus in FCD patients." (PMID 38074125, 2023).
focal segmental glomerulosclerosis (1 paper, 2020). A renal disorder characterized by sclerotic lesions in the glomeruli. "Deletion of the Tsc2 gene in podocytes increases glomerular size and the characteristics of focal segmental glomerulosclerosis (FSGS) and causes end-stage renal dysfunction concomitant with impaired autophagy in podocytes." (PMID 32191726, 2020).
geographic atrophy (1 paper, 2021). "Similar to deletion of Tsc1, mice with deletion of Tsc2 in rods develop AMD-like pathologies, including accumulation of apolipoproteins, migration of microglia, geographic atrophy, and neovascular pathologies." (PMID 34208233, 2021).
head and neck cancer (1 paper, 2021). A primary or metastatic malignant neoplasm affecting the head and neck. "Of the four cell lines tested, the HPV-positive head and neck cancer cell line UM-SCC47 had several unique characteristics, such as high raptor expression, and treatment with 6 μM temsirolimus inhibited p70 S6 kinase and 4E-BP1 phosphorylation and the activation of TSC2." (PMID 33482765, 2021).